UBR4 (ubiquitin protein ligase E3 component n-recognin 4)
Description:
E3 ubiquitin-protein ligase involved in different protein quality control pathways in the cytoplasm. Component of the N-end rule pathway: ubiquitinates proteins bearing specific N-terminal residues that are destabilizing according to the N-end rule, leading to their degradation. Recognizes both type-1 and type-2 N-degrons, containing positively charged amino acids (Arg, Lys and His) and bulky and hydrophobic amino acids, respectively. Does not ubiquitinate proteins that are acetylated at the N-terminus. Together with UBR5, part of a cytoplasm protein quality control pathway that prevents protein aggregation by catalyzing assembly of heterotypic 'Lys-11'-/'Lys-48'-linked branched ubiquitin chains on aggregated proteins, leading to substrate recognition by the segregase p97/VCP and degradation by the proteasome: UBR4 probably synthesizes mixed chains containing multiple linkages, while UBR5 is likely branching multiple 'Lys-48'-linked chains of substrates initially modified. Together with KCMF1, part of a protein quality control pathway that catalyzes ubiquitination and degradation of proteins that have been oxidized in response to reactive oxygen species (ROS): recognizes proteins with an Arg-CysO3(H) degron at the N-terminus, and mediates assembly of heterotypic 'Lys-63'-/'Lys-27'-linked branched ubiquitin chains on oxidized proteins, leading to their degradation by autophagy. Catalytic component of the silencing factor of the integrated stress response (SIFI) complex, a multiprotein complex that turns off the mitochondrial stress response after a specific stress event has been resolved. The SIFI complex ubiquitinates and degrades (1) components of the HRI-mediated signaling of the integrated stress response, such as DELE1 and EIF2AK1/HRI, as well as (2) unimported mitochondrial precursors such as ABHD10. Within the SIFI complex, UBR4 initiates ubiquitin chains that are further elongated or branched by KCMF1. Mediates ubiquitination of ACLY, leading to its subsequent degradation. Together with clathrin, forms meshwork structures involved in membrane morphogenesis and cytoskeletal organization.
Synonyms: p600; RBAF600; KIAA0462; KIAA1307; ZUBR1
Tractability: Antibody: its Gene Ontology location is reachable by antibodies, with high confidence. PROTAC: ubiquitination databases record sites on it; its protein half-life has been measured.
Target class: Enzyme; Transferase
Gene: Protein-coding gene on chromosome 1 (19,074,510 to 19,210,266, reverse strand). Ensembl gene ENSG00000127481.
Subcellular location: Cytoplasm; Cytoplasm, cytoskeleton; Endosome; Nucleus
Subcellular location (Human Protein Atlas): Nucleoplasm; Acrosome; Centrosome; Cytosol; Flagellar centriole; Perinuclear theca; Principal piece
Pathways (Reactome):
Immune System: Antigen processing: Ubiquitination & Proteasome degradation; Neutrophil degranulation
Disease: Dengue virus activates/modulates innate and adaptive immune responses
Gene Ontology:
Molecular function: protein binding; ubiquitin protein ligase activity; ubiquitin-like ligase-substrate adaptor activity; calmodulin binding; zinc ion binding
Biological process: cytoplasm protein quality control; cytoplasm protein quality control by the ubiquitin-proteasome system; HRI-mediated signaling; negative regulation of fatty acid biosynthetic process; negative regulation of HRI-mediated signaling; proteasome-mediated ubiquitin-dependent protein catabolic process; protein branched polyubiquitination; protein K11-linked ubiquitination; protein K27-linked ubiquitination; protein K48-linked ubiquitination; protein quality control for misfolded or incompletely synthesized proteins; response to oxidative stress; ubiquitin-dependent protein catabolic process; ubiquitin-dependent protein catabolic process via the N-end rule pathway; endosome organization; positive regulation of autophagy; protein ubiquitination
Cellular component: cytoplasm; cytosol; membrane; nucleoplasm; ubiquitin ligase complex; endosome; ficolin-1-rich granule membrane; nucleus; plasma membrane; specific granule membrane; tertiary granule membrane; cytoskeleton
Genetic constraint (gnomAD): Loss-of-function variants: 123 observed, 589.95 expected, observed/expected ratio (o/e) 0.21, 90% interval 0.18 to 0.24. The upper end of that interval is the gene's LOEUF score, 0.24, which puts it in group 1 of 6, group 1 being the genes least tolerant of losing a copy. Missense variants: 4,782 observed, 6,670.2 expected, observed/expected ratio (o/e) 0.72, 90% interval 0.7 to 0.73. Synonymous variants: 2,428 observed, 2,556.4 expected, observed/expected ratio (o/e) 0.95, 90% interval 0.92 to 0.98.
Homologues: Orthologues: chimpanzee UBR4 (99% identical), macaque UBR4 (99% identical), rabbit UBR4 (98% identical), dog UBR4 (98% identical), pig UBR4 (98% identical), guinea pig UBR4 (98% identical), mouse Ubr4 (97% identical), rat Ubr4 (97% identical), tropical clawed frog ubr4 (87% identical), zebrafish ubr4 (86% identical), Drosophila melanogaster poe (40% identical), Caenorhabditis elegans ubr-4 (20% identical).
Diseases named in the same sentence as UBR4 in open-access papers:
UBR4 is named in the same sentence as 43 diseases in open-access papers, as found by Europe PMC text mining. Sharing a sentence is not in itself a finding about the gene and the disease. The quoted sentences say what the papers report.
Ataxia (4 papers, 2017 to 2025). Ataxia refers to impaired coordination of voluntary muscle movement. "Deletion of the SIFI subunit UBR4 disrupts heart, brain and yolk-sac development, resulting in embryonic lethality, and mutations in UBR4 cause ataxia and early onset dementia." (PMID 40328314, 2025). "Revealing flexibility of the scaffold, the dimerization interfaces show ~10° rotations towards each other, which occur around a hinge close to UBR4 Ala2581, which is mutated in ataxia, and Arg2584, which is altered in cancer." (PMID 40328314, 2025). "As mutations in UBR4 cause ataxia and early-onset dementia, we asked whether the quality control function of UBR4 safeguards specific pathways to ensure cellular homeostasis." (PMID 38297121, 2024). "In this study, we conducted next-generation sequencing in Korean EA patients to identify pathogenic mutations of five known EA genes (KCNA1, CACNA1A, CACNB4, SLC1A3, and UBR4), and explored candidate genes that cause EA as a secondary phenotype or cerebellar ataxia." (PMID 29062094, 2017). "Thus, the UBR4 mutation may result in abnormal Ca2+ signaling within the neuron and development of ataxia." (PMID 29062094, 2017). "UBR4 had a greater likelihood of pathogenicity than SPG2, as UBR4 is ubiquitin ligase protein that interacts with calmodulin and may potentially disrupt calcium sensor in neurons as hypothesis for ataxia." (PMID 37008993, 2023).
atherosclerosis (3 papers, 2022 to 2024). A disease characterized by the build-up of fatty material and calcium deposition in the arterial wall resulting in partial or complete occlusion of the arterial lumen. "Additionally, circ-UBR4 and miR-29a, as diagnostic biomarkers, are increased in serum from atherosclerosis patients." (PMID 38515760, 2024). "The aim of our study is to disclose the role and underlying molecular mechanisms of circular RNA ubiquitin protein ligase E3 component n-recognin 4 (circ-UBR4) in atherosclerosis (AS)." (PMID 37693837, 2023). "Taken together, circ_UBR4/miR-107/ROCK1 pathway has a possible role in the development of atherosclerosis through modulation of proliferative ability, migration, and cell cycle transition of human VSMCs." (PMID 36177350, 2022). "Moreover, five notable crosstalk pathways, circ-UBR4/miR-637/FOXO4, circ-UBR4/miR-107/ROCK1, circ-UBR4/miR-491-5p/NRP2, circ-UBR4/miR-185-5p/FRS2 and circ-CHFR/miR-214-3p/PAPPA axis, regulate VSMC migration and growth to improve atherosclerosis." (PMID 38515760, 2024).
episodic ataxia (3 papers, 2018 to 2022). "Along similar lines, disease-linked variants of UBR4 have been identified in patients suffering from episodic ataxia (EA), a neurological disorder that is associated with altered biosynthesis and trafficking of calcium and potassium channels to the PM47–52." (PMID 35332162, 2022). "In a Korean study, where whole exome sequencing was performed in 39 individuals with episodic ataxia, four new possible or probable pathogenic variants in UBR4 [p.(Tyr4877Cys), p.(Arg4111His), p.(Ala5042Val), and p.(Ala2581Val)] have been identified." (PMID 34566847, 2021). "A missense variant in UBR4 (p.Arg5091His) was found to segregate with episodic ataxia in a large Irish pedigree." (PMID 29770609, 2018).
gastric cancer (3 papers, 2018 to 2022). A primary or metastatic malignant neoplasm involving the stomach. "Gene CNTFR has been implicated in rheumatoid arthritis, a chronic inflamatory disorder, and UBR4 in anorectal malformations and stomach cancer." (PMID 35105309, 2022). "The UBR4 gene, a host of RP5-1126H10.2, is upregulated in a metastatic breast tumor cell line, and its inhibition suppresses the invasiveness of gastric cancer." (PMID 34557494, 2021).
Autoimmunity (2 papers, 2024). The occurrence of an immune reaction against the organism's own cells or tissues. "Here, we report the mechanisms of how IKZF1 and UBR4 variants in a case of familial IgG4-RD cause autoimmunity with a dominant bias for Th2 polarization." (PMID 38885295, 2024). "The discovery of defective protein degradation mediated by the UBR4 variant suggests that regulation of protein turnover also contributes to autoimmunity." (PMID 39145453, 2024).
dementia (2 papers, 2017 to 2024). Loss of intellectual abilities interfering with an individual's social and occupational functions. "Although the phenotype associated with AKAP6 is nonspecific developmental delay and seizures, the phenotype we observe in the two families with different heterozygous variants in UBR4 is highly specific and consists of early onset dementia." (PMID 28600779, 2017). "We therefore propose that pathologies driven by persistent stress induction or delayed stress response inactivation, including early-onset dementia caused by UBR4 mutations, could benefit from compound-induced stress response silencing." (PMID 38297121, 2024). "Similarly, we have identified independent deleterious variants in UBR4 in two families with very early onset dementia (16-2737 and 16-2768)." (PMID 28600779, 2017). "Two of these genes were independently mutated in more than one family with similar phenotypes, which substantiates their link to human disease (AKAP6 in intellectual disability and UBR4 in early dementia)." (PMID 28600779, 2017).
lung carcinoma (2 papers, 2025). "UBR4 knockout (ΔUBR4) in A549 lung cancer cells induced cellular senescence with defective mitochondria." (PMID 40531870, 2025). "In response to high glucose levels, ACLY is acetylated at K540, K546, and K554 by lysine acetyltransferase (KAT2B), reducing the binding between ACLY and the RING-type E3 ubiquitin ligase UBR4, thereby promoting lung cancer progression." (PMID 39944823, 2025). "Together, our data clearly demonstrate the tumor-promoting characteristics of UBR4 in both lung cancer cells and mouse models, indicating that its deletion reduces tumor growth and induces senescence." (PMID 40531870, 2025). "UBR4 deletion resulted in cell cycle arrest, a hypersecretory and proinflammatory phenotype, and paracrine senescence induction in cultured lung cancer cells, along with a substantial delay in ΔUBR4 LUAD tumor growth in an in vivo mouse xenograft model." (PMID 40531870, 2025).
neuroblastoma (2 papers, 2018 to 2022). Neuroblastoma (NB) is the most common solid, extracranial childhood tumor. "Along these lines, knocking down Ubr4 expression in murine neuroblastoma (Neuro-2a) cells also reduced the abundance of ectopically expressed V5-tagged PER2." (PMID 35332162, 2022).
Nystagmus (2 papers, 2017 to 2021). Rhythmic, involuntary oscillations of one or both eyes related to abnormality in fixation, conjugate gaze, or vestibular mechanisms. "Two patients with UBR4 mutation (patients 26 and 28) presented with recurrent vertigo/dizziness and imbalance lasting several hours with interictal nystagmus beginning in their fifth or sixth decades." (PMID 29062094, 2017).
anorectal malformation (1 paper, 2019). "We analyzed the UBR4 expressions in the colons of HSCR patient and anorectal malformation (ARM) patient as control by real-time polymerase chain reaction (qPCR)." (PMID 31830949, 2019).
autoimmune disease (1 paper, 2024). A disorder resulting from loss of function or tissue destruction of an organ or multiple organs, arising from humoral or cellular immune responses of the individual to their own tissue constituents. "Although UBR4 has so far not been implicated, ubiquitination has been identified as a critical component in the development of autoimmune disease." (PMID 38885295, 2024).
brucellosis (1 paper, 2025). Brucellosis is a bacterial infection that spreads from animals to people via unpasteurized dairy products or by exposure to contaminated animal products or infected animals. "UBR4 is involved in immune responses, as seen in its association with brucellosis resistance." (PMID 41514760, 2025).
cervical cancer (1 paper, 2016). A primary or metastatic malignant neoplasm involving the cervix. "High-risk E7 proteins target PTPN14 for proteasome-mediated degradation, which requires the ubiquitin ligase UBR4, and PTPN14 is degraded by the proteasome in HPV-positive cervical cancer cell lines." (PMID 27651363, 2016).
colorectal cancer (1 paper, 2024). A primary or metastatic malignant neoplasm that affects the colon or rectum. "The interaction between endogenous MLH1 and UBR4 was also confirmed in both cervical and colorectal cancer cells." (PMID 39032648, 2024).
endometrial cancer (1 paper, 2025). Primary or metastatic malignant neoplasm involving the endometrium (mucous membrane that lines the endometrial cavity). "Further investigation of genomic variations demonstrated high-frequency SNVs and CNVs in key regulators such as PTEN, ARID1A, and UBR4, particularly in endometrial cancer, where PTEN and ARID1A mutations were significantly enriched." (PMID 40396172, 2025).
Hirschsprung disease (1 paper, 2019). Hirschsprung disease (HSCR) is a congenital intestinal motility disorder that is characterized by signs of intestinal obstruction due to the presence of an aganglionic segment of variable extent in the terminal part of the colon. "Recently, pathogenic alleles within ubiquitin N-recognin domain-containing E3 ligase 4 (UBR4) gene have been shown to be associated with Hirschsprung disease (HSCR)." (PMID 31830949, 2019).
Huntington disease (1 paper, 2024). Huntington disease (HD) is a rare neurodegenerative disorder of the central nervous system characterized by unwanted choreatic movements, behavioral and psychiatric disturbances and dementia. "Our results also suggest the involvement of K48/K63 branched Ub in Huntington’s disease, as we identified the huntingtin-interacting protein HIP1 and UBR4, which has been linked to K11/K48 branched ubiquitination on mutant huntingtin, as specific interactors of Br Ub3." (PMID 38803224, 2024).
IgG4-related disease (1 paper, 2024). "In familial IgG4-related disease, IKZF1 and UBR4 gene variants break T cell tolerance and concomitantly induce a Th2 response." (PMID 38885295, 2024).
liver fibrosis (1 paper, 2024). "Based on the ceRNA network, lncRNA TNFRSF10A-DT/has-mir-873–5/RCC2, UBR4, and the AKR7A2 axis may construct a ceRNA network to participate in the progression of liver fibrosis." (PMID 38378545, 2024).
lung adenocarcinoma (1 paper, 2025). A carcinoma that arises from the lung and is characterized by the presence of malignant glandular epithelial cells. "Here, we describe the tumorigenic involvement of ubiquitin protein ligase E3 component n-recognin 4 (UBR4), an E3 ubiquitin ligase of the N-degron pathway, in lung adenocarcinoma (LUAD)." (PMID 40531870, 2025). "Our study identifies a role of UBR4 in regulating mitochondrial quality, cellular aging, and tumor growth in lung adenocarcinoma (LUAD)." (PMID 40531870, 2025). "We aimed to understand the functional significance of UBR4 in tumorigenesis, particularly in lung adenocarcinoma (LUAD), where UBR4 messenger RNA (mRNA) expression is significantly enhanced; however, its underlying mechanism remains unknown." (PMID 40531870, 2025).
melanoma (1 paper, 2023). A malignant, usually aggressive tumor composed of atypical, neoplastic melanocytes. "Our studies extend understanding of this oncoprotein by demonstrating UHRF1/UBE2L6/UBR4-mediated EZH2 promotion to enhance LPC phenotypes and disease progression in melanoma, providing a mechanism as to how higher levels of EZH2 are associated with late-stage disease." (PMID 36906655, 2023). "Tumor-suppressive and anti-metastatic roles of UBE2L6 in vivo have not been described, and we found are mediated in melanoma by the ubiquitin-conjugating function of UBE2L6, working cooperatively with the E3 ligase UBR4, to induce EZH2 ubiquitination and protein degradation." (PMID 36906655, 2023).
muscular atrophy (1 paper, 2024). The loss of muscle tissue due to inactivity or disease. "The role of UBR4 E3 activity in promoting various diseases such as cancer and muscular atrophy would imply that modulation of UBR4 hemiRING E3 activity might have therapeutic value (for example, by disruption of the UBE2A–hemiRING interface)." (PMID 38182926, 2024).
ovarian carcinoma (1 paper, 2021). A malignant neoplasm originating from the surface ovarian epithelium. "Secondly, we identified more accurate and reliable hub genes including EIF3M, RPS27A, SNRNP200 and UBR4, and we also performed an enrichment analysis to characterize the role of AS in ovarian cancer." (PMID 34001978, 2021). "In this paper, we identified the potential gene with prognosis-related AS event in ovarian carcinomas (the multiple genes presented in the network), and EIF3M, RPS27A, SNRNP200 and UBR4 were found at the core of gene interaction network." (PMID 34001978, 2021).
renal carcinoma (1 paper, 2024). A carcinoma arising from the epithelium of the renal parenchyma or the renal pelvis. "A recent study showed that UBR4, an E3 ubiquitin ligase, is involved in the apoptosis of renal cancer cells." (PMID 38538582, 2024).
retinoblastoma (1 paper, 2016). A malignant tumor that originates in the nuclear layer of the retina. "In addition, our results are consistent with the previously identified role of UBR4 in retinoblastoma-independent transformation, since the degradation of PTPN14 in the presence of E7 requires UBR4." (PMID 27651363, 2016).
sarcopenia (1 paper, 2021). Progressive decline in muscle mass due to aging which results in decreased functional capacity of muscles. "In summary, these findings indicate that, as exemplified by UBR4 loss, interventions that promote hypertrophy can have contrasting effects on the two components of sarcopenia, i.e., muscle mass and strength." (PMID 33658508, 2021). "Tamoxifen-induced muscle-specific UBR4 knockout mice (UBR4 mKO) were also used to further probe the consequences of UBR4 loss on sarcopenia." (PMID 33658508, 2021).
virus infection (1 paper, 2024). "Combined with previous studies, we have determined the following critical roles of HUWE1, UBR4, and UBR5 in virus infection." (PMID 38709105, 2024).